SCG5 (secretogranin V)
Description:
Acts as a molecular chaperone for PCSK2/PC2, preventing its premature activation in the regulated secretory pathway. Binds to inactive PCSK2 in the endoplasmic reticulum and facilitates its transport from there to later compartments of the secretory pathway where it is proteolytically matured and activated. Also required for cleavage of PCSK2 but does not appear to be involved in its folding. Plays a role in regulating pituitary hormone secretion. The C-terminal peptide inhibits PCSK2 in vitro.
Synonyms: SGNE1; 7B2; SgV; P7B2
Tractability: Antibody: UniProt places it where antibodies can reach, with medium confidence; UniProt predicts a signal peptide or a membrane-spanning region; its Gene Ontology location is reachable by antibodies, with medium confidence. PROTAC: ubiquitination databases record sites on it; its protein half-life has been measured.
Gene: Protein-coding gene on chromosome 15 (32,641,385 to 32,697,098, forward strand). Ensembl gene ENSG00000166922.
Subcellular location: Secreted
Gene Ontology:
Molecular function: protein binding; enzyme inhibitor activity; enzyme regulator activity; GTP binding
Biological process: intracellular protein transport; peptide hormone processing; regulation of hormone secretion; neuropeptide signaling pathway
Cellular component: extracellular region; secretory granule; nucleus
Genetic constraint (gnomAD): Loss-of-function variants: 14 observed, 17.97 expected, observed/expected ratio (o/e) 0.78, 90% interval 0.51 to 1.22. The upper end of that interval is the gene's LOEUF score, 1.22, which puts it in group 5 of 6, group 1 being the genes least tolerant of losing a copy. Missense variants: 145 observed, 207.19 expected, observed/expected ratio (o/e) 0.7, 90% interval 0.61 to 0.8. Synonymous variants: 84 observed, 74.37 expected, observed/expected ratio (o/e) 1.13, 90% interval 0.95 to 1.35.
Homologues: Orthologues: chimpanzee SCG5 (100% identical), macaque SCG5 (99% identical), guinea pig SCG5 (96% identical), pig SCG5 (96% identical), dog SCG5 (93% identical), mouse Scg5 (92% identical), rat Scg5 (92% identical), zebrafish scg5 (76% identical), Drosophila melanogaster 7B2 (31% identical), Caenorhabditis elegans sbt-1 (27% identical).
Diseases named in the same sentence as SCG5 in open-access papers:
SCG5 is named in the same sentence as 40 diseases in open-access papers, as found by Europe PMC text mining. Sharing a sentence is not in itself a finding about the gene and the disease. The quoted sentences say what the papers report.
colorectal cancer (9 papers, 2014 to 2023). A primary or metastatic malignant neoplasm that affects the colon or rectum. "It has also been shown that SNPs near GREM1 and SCG5 are significantly related to increased risk of colorectal cancer (CRC)." (PMID 33962391, 2021). "This work helps characterize the relationship between variants in the SCL22A3, SCG5, GREM1, and STXBP5-AS1 genes and colorectal cancer in a diverse Indonesian population." (PMID 33976257, 2021). "Interestingly, seven of the shared significant genes have been associated to colorectal cancers, including UTP23, GREM1, SCG5, SMAD7, CABLES2, LAMA5, and PREX1." (PMID 32245788, 2020). "Several recent studies have revealed that SCG5 may be involved in colorectal cancer tumorigenesis by affecting proliferation." (PMID 29796168, 2018). "The nominally significant SNPs included colorectal cancer GWAS SNPs in SMAD7, C11orf93, SCG5, and ATF1, and breast cancer SNPs related to CDKN2B-AS1, FGFR2, GDI2, CDYL2." (PMID 29698419, 2018). "The role of SCG5 in colorectal cancer has not been well characterized, while much is known about its neighbor GREM1’s role in colorectal cancer." (PMID 33976257, 2021).
pancreatic cancer (4 papers, 2020 to 2022). "SCG5, CRYBA2, CPE and CHGB genes are associated with the prognosis of pancreatic cancer, and their low expression suggests a poor prognosis." (PMID 33164330, 2020). "Prognostic analysis showed the expression levels of four genes were significantly correlated with the overall survival time of patients with pancreatic cancer, namely SCG5, CRYBA2, CPE and CHGB." (PMID 33164330, 2020). "This signifies that SCG5 may be a systemic humoral factor and may contribute to cachexia in pancreatic cancer, which should be verified further." (PMID 36059698, 2022). "In addition, the level of SCG5 expression was lower in pancreatic cancer patients with low BMI, although it is unclear whether SCG5 induces cachexia or adipopenia." (PMID 36059698, 2022). "The low expression of secretogranin V (SCG5) could predict a poorer prognosis of pancreatic cancer." (PMID 34903206, 2021). "Finally, circulating level of SCG5 in the plasma was determined from the independent cohort (non-tumor = 25 and pancreatic cancer = 25)." (PMID 36059698, 2022).
breast carcinoma (3 papers, 2018 to 2022). "SCG5 encodes a neuroendocrine protein and is overexpressed in brain metastatic breast cancer and breast cancer stem cells." (PMID 36142451, 2022).
Obesity (3 papers, 2007 to 2022). Accumulation of substantial excess body fat. "More importantly, we have demonstrated that an increase in Scg5 expression is correlated with decreases in body weight and obesity in two congenic mouse models and overexpression results in an in vivo increase in 7B2 protein levels and PCSK2 enzymatic activity." (PMID 18439298, 2008). "Additionally, if differential expression of Scg5 is causal for Wg5 (in HG2DF2 mice) and Wg2b (in B62D-3 mice), then its expression must correlate with growth traits and indeed its expression was significantly negatively correlated (P < 0.01) with body weight and obesity in both crosses." (PMID 18439298, 2008). "Scg5 knockout mice (on a 129/SvEv background) exhibit a postnatal lethal phenotype in which all mice die by 5 weeks of age (due to intermediate lobe ACTH hypersecretion and rampant corticosteronemia); however, adrenalectomy rescues these animals and reveals a late-onset obesity phenotype." (PMID 18439298, 2008).
Glucose intolerance (2 papers, 2007 to 2015). Glucose intolerance (GI) can be defined as dysglycemia that comprises both prediabetes and diabetes. "Also Scg5 (SGNE1) might impair glucose intolerance and insulin resistance, which was consistent with the insulin resistant phenotype of GK strain." (PMID 26529237, 2015).
lung carcinoma (2 papers, 2025). "The SCG family has been established as relevant to brain diseases as highlighted in the analysis of key genes associated with lung cancer, and SCG5 was reconfirmed in the brain cancer dataset." (PMID 40608007, 2025).
Parkinson disease (2 papers, 2022 to 2025). A progressive degenerative disorder of the central nervous system characterized by loss of dopamine producing neurons in the substantia nigra and the presence of Lewy bodies in the substantia nigra and locus coeruleus. "SCG5 is a secreted chaperone protein that suppresses aggregation of neurodegeneration related proteins such as amyloid-β (Aβ)-derived peptides and tau in AD and α-synuclein in Parkinson disease (PD)." (PMID 35911978, 2022).
prostate carcinoma (2 papers, 2019 to 2020). A carcinoma that arises from epithelial cells of the prostate gland. "Although there were no studies to discuss the roles of SCG5 in cancer, its family members secretogranin II and III have been seen to be overexpressed in prostate cancer and small cell lung carcinoma, suggesting SCG5 may also be oncogenic for LSCC." (PMID 31565549, 2019).
thyroid cancer (2 papers, 2016 to 2019). "A novel diagnostic test that measures the expression of a 3-gene signature (DPP4, SCG5 and CA12) has demonstrated promise in thyroid carcinoma assessment." (PMID 27776138, 2016). "CD26, secretogranin V (SCG5) and carbonic anhydrase XII (CA12) are a three-gene signature that can distinguish malignant thyroid cancers, and is useful for preoperative diagnosis of thyroid cancer." (PMID 31194830, 2019).
Cachexia (1 paper, 2022). Severe weight loss, wasting of muscle, loss of appetite, and general debility related to a chronic disease. "Aligning with the result showing positive correlation between plasma SCG5 and BMI (adiposity), this implies that SCG5 may be a systemic regulator of adipose tissue homeostasis and may contribute to cachexia in patients with PAC." (PMID 36059698, 2022).
cerebral amyloid angiopathy (1 paper, 2025). "Scg5 is a chaperone protein (and copper metabolism indicator) that prevents aggregation of other secreted proteins; expression decreases with severity of AD or cerebral amyloid angiopathy." (PMID 40979532, 2025).
glioma (1 paper, 2022). A benign or malignant brain and spinal cord tumor that arises from glial cells (astrocytes, oligodendrocytes, ependymal cells). "BMP2 and HEY2 were identified as protective factors (HR < 1), and NUP107, DRAM1, F2R, PXDN, RNF19A, and SCG5 were identified as risk factors for glioma (HR > 1)." (PMID 36245971, 2022). "The epigenetic inactivation of secretogranin V (SCG5/SGNE1/7B2) was a frequent early event in glioma formation, resulting in significant downregulation of SCG5/SGNE1/7B2 expression." (PMID 36245971, 2022). "QRT-PCR further supported significantly higher DRAM1 and lower SCG5 relative mRNA expression in gliomas." (PMID 36245971, 2022). "In our study, the results of human tissue-based IHC staining and QRT-PCR experiments well confirmed the biological value of F2R, HEY2, PXDN, RNF19A, SCG5, and DRAM1 in glioma." (PMID 36245971, 2022).
hereditary mixed polyposis syndrome (1 paper, 2021). "A duplication that spans the 3’end of SCG5 and the immediate, adjacent upstream region of GREM1 is associated with hereditary mixed polyposis syndrome (HMPS) as well as tumorigenesis in juvenile polyposis." (PMID 33976257, 2021).
neuroendocrine tumors (1 paper, 2018). "Secretogranin V (SCG5) is a member of the chromogranin and secretogranin family and is expressed in neuroendocrine tumors, functioning in neuroendocrine differentiation in cancer." (PMID 29796168, 2018).
oral squamous cell carcinoma (1 paper, 2023). "The expression of AXL, SCG5, VOPP1, DCBLD2 and DRAM in oral squamous cell carcinoma were significantly higher in the TCGA database than in normal tissues." (PMID 37925175, 2023).
primitive neuroectodermal tumors of the brain (1 paper, 2025). "Secretogranin II (SCG2) has been confirmed to be related to primitive neuroectodermal tumors of the brain, while secretogranin V (SCG5) primarily regulates the secretion of pituitary hormones, preventing the aggregation of secretion proteins linked to certain diseases." (PMID 40608007, 2025).
pulmonary fibrosis (1 paper, 2022). Chronic progressive interstitial lung disorder characterized by the replacement of the lung tissue by connective tissue, leading to progressive dyspnea, respiratory failure, or right heart failure. "In addition, no other potential markers IGFL2, NECAB1, SCG5 were found to play a role in pulmonary fibrosis." (PMID 36507532, 2022).
tongue squamous cell carcinoma (1 paper, 2023). A squamous cell carcinoma that arises from the tongue. "Eight genes were shown to be related to the prognosis in patients with tongue squamous cell carcinoma (AXL, SCG5, VOPP1, DCBLD2, DRAM, DUSP1, AQP5, BLNK)." (PMID 37925175, 2023).
tumor (10 papers, 2010 to 2025). "The profiled tumor cells expressed most general PNEC markers (e.g. SCG5, CHGB, SCG2, PCSK1N, CHGA, SCG3) indicating retention of PNEC identity." (PMID 36469459, 2022). "In the case of T stage, which is classified by the size of the tumor, the expression level of SCG5 decreased significantly in T3 compared to T2." (PMID 36059698, 2022). "Although the results have the limitation of making a clear conclusion, this result, at least in part, confirms machine learning predictions and reveals that the expression level of SCG5 reduces as the severity of the tumor grows, such as tumor size or lymph node metastasis." (PMID 36059698, 2022). "In addition, several studies reveal that secretogranin V (SCG5) is related to tumor prognosis." (PMID 37925175, 2023). "The targets identified by the tumor vs tumor comparisons (EMX2, PTPRN, SCG5) required a representative cohort for ROC analysis; these three genes concern only UCEC and PAAD tumors." (PMID 35361846, 2022). "After removing the individual samples from the database, we obtained 20 pairs of paired samples and then compared the expression levels of CCL20, SCG5, SPP1, FOLR3, and KRT75 genes in tumor tissues vs. normal tissues." (PMID 36684241, 2022). "Upregulated neuropeptide genes, such as PTHLH, Gastrin (GAST), Secretogranin V (SCG5), Neuromedin B (NMB), and Apelin (APLN), were positively correlated with upregulated neurotrophic factors, which were consistent with their roles in tumor progression and neuroimmune crosstalk." (PMID 40805163, 2025). "For PTPRN and SCG5 expression, PAAD was compared to ESCA, since it was the closest cohort in terms of size (no tumor with a similar site of origin to PAAD was included in this study)." (PMID 35361846, 2022).
cancer (8 papers, 2014 to 2025). A tumor composed of atypical neoplastic, often pleomorphic cells that invade other tissues. "The eight mRNAs selected for further analysis, AXL, SCG5, VOPP1, DCBLD2 and DRAM1 are cancer-promoting genes, DUSP1, AQP5 and BLNK are cancer suppressor genes." (PMID 37925175, 2023). "The results revealed five cancer-promoting genes (AXL, SCG5, VOPP1, DCBLD2, DRAM1), and three tumor suppressor genes (DUSP1, AQP5, BLNK)." (PMID 37925175, 2023). "We also investigated the correlation between SCG5 expression and clinicopathological characteristics of PAC (i.e., TNM Classification of Malignant Tumors)." (PMID 36059698, 2022). "The analysis showing the degree of association between SCG5 plasma protein and BMI also demonstrates that this association exists not only in cancer patients but also in donors without cancer, implying that plasma SCG5 has a role in both physiology and pathology." (PMID 36059698, 2022). "Taken together, these results strongly supported the excellent anti-cancer effects of BRD4 inhibition by JQ1 in sunitinib-resistant ccRCC and suggested that SCG5, SPOCD1, RGS19, and ARHGAP22 may be novel direct targets of the epigenetic reader BRD4 in sunitinib-resistant ccRCC." (PMID 29796168, 2018).
neurodegenerative disease (3 papers, 2020 to 2024). A disorder of the central nervous system characterized by gradual and progressive loss of neural tissue and neurologic function. "SCG5 may function as a chaperone protein involved in anti-aggregation processes in varying neurodegenerative diseases." (PMID 38191511, 2024).
SCG5 also shares sentences with these, for which no sentence is quoted: Alzheimer disease (2 papers); infection (2); Insulin resistance (2); autism (1); brain cancer (1); brain diseases (1); cardiovascular diseases (1); Cognitive impairment (1); frontotemporal dementia (1); juvenile polyposis (1); lipodystrophy (1); liver disease (1); maturity-onset diabetes of the young (1); medulloblastoma (1); metabolic disease (1); neuroblastoma (1); pancreatic adenocarcinoma (1); small cell lung carcinoma (1); type 2 diabetes (1).